PALB2 (partner and localizer of BRCA2)
Diseases named in the same sentence as PALB2 in open-access papers (continued):
Sharing a sentence is not in itself a finding about the gene and the disease.
prostate carcinoma (continued). "PALB2 (Partner and Localizer of BRCA2) mediates the interaction between BRCA1 and BRCA2, plays a role in the nuclear localization of BRCA2, aids in RAD51 loading at resected DNA breaks, and pathogenic mutations in PALB2 have been found to predispose to breast, ovarian, and prostate cancer." (PMID 34065235, 2021). "For example, most hereditary cancer panels include genes for breast, ovarian and colon cancer – and includes the five main genes for prostate cancer discussed here (BRCA1, BRCA2, CHEK2, ATM, PALB2)." (PMID 35732815, 2022). "In several tumor types, particularly breast, ovarian, pancreatic, and prostate cancers, a strong correlation was observed between increased gLOH and biallelic alterations in other HR genes beyond BRCA1 and BRCA2, including BARD1, PALB2, FANCC, RAD51C, and RAD51D." (PMID 37761329, 2023). "PROREPAIR-B is an ongoing prospective study to evaluate the outcomes of patients with metastatic castrate-resistant prostate cancer with and without germline ATM/BRCA1/BRCA2/PALB2 mutations." (PMID 35732815, 2022). "We first assessed the frequency of PALB2 and BARD1 alterations in advanced prostate cancer." (PMID 35768576, 2022). "They found that PALB2 carriers were not more common in prostate cancer patients overall, but were common in those diagnosed with aggressive prostate cancers of high grade (Gleason score 8–10) than noncarriers (64.3% vs. 18.1%, p < 0.0001)." (PMID 35732815, 2022). "PALB2 carriers had significant family histories in breast and prostate cancers when comparing with non-carriers (p-value = 0.037 and 0.005, respectively)." (PMID 34439348, 2021). "Moreover, there is good evidence from prostate cancer that the PARPi olaparib is effective in tumours with alterations in RAD51C, RAD51D, CHEK2, PALB2, RAD54L, and BARD1." (PMID 34680387, 2021). "There were 5271 prostate cancer patients included with 18 (0.3%) having germline BRCA1 alterations, 139 (2.6%) with BRCA2 alterations, 49 (0.9%) with germline ATM alterations, 15 (0.3%) with germline PALB2 alterations, and 27 (0.5%) with germline CHEK2 alterations." (PMID 40361359, 2025). "Family history of prostate cancer was seen in 15.4% of PALB2 carriers but in only 1.7% of BRCA1 carriers (p-value = 0.001); there was no significant different between PALB2 and BRCA2 carriers (p-value = 0.594)." (PMID 34439348, 2021).
Lynch syndrome (49 papers, 2015 to 2026). An autosomal dominant hereditary neoplastic syndrome characterized by the development of colorectal carcinoma and a high risk of developing endometrial carcinoma, gastric carcinoma, ovarian carcinoma, renal pelvis carcinoma, and small intestinal carcinoma. "Beyond the well-established BRCA1/2 and Lynch syndrome genes, large panels can identify pathogenic variants in other moderate-to-high penetrance genes, such as PALB2 and CHEK2, which are implicated in both breast and colorectal cancer risks." (PMID 41378290, 2025). "Other genes, such as CHEK2, ATM, and PALB2 and Lynch syndrome genes, are also implicated in ovarian cancer." (PMID 32127576, 2020). "Those with a pathogenic variant in CDKN2A, BRCA2, PALB2, or a Lynch syndrome-associated gene and a first degree relative are potential candidates for screening." (PMID 30186770, 2018). "PALB2 has recently been reported as a moderate risk OC gene and Lynch Syndrome (MMR) genes may be found in another 1% OC patients." (PMID 34503154, 2021). "Delayed oophorectomy also may currently be taken into consideration in the case of other gene mutations predisposing patients to gynecological malignancies, such as MLH1, MSH6, and PMS2 in Lynch syndrome and PALB2, whose cancer risk range estimates overlap with BRCA." (PMID 36835955, 2023). "Other, less common, gene mutations include CHEK2, PALB2, CDH1, MLH1 (associatedwith Lynch syndrome), and RET." (PMID 38993971, 2024). "In our study, TTN DCM type 1G, KCNQ1 LQTS type 1, MYBPC3 HCM type 4, and TMEM43 arrhythmogenic right ventricular dysplasia type 5 were the most frequent CVD, and MSH6 Lynch syndrome and PALB2 HBC were the most frequent CPC among ACMG SFs." (PMID 36635046, 2023). "The percent of germline LP/P variants within the traditional genetic counseling and tumor DNA safety net groups was similar for BRCA2 (40% versus 32%), PALB2 (3% versus 8%), and Lynch syndrome genes (collectively 19% versus 13%)." (PMID 36261688, 2023). "High risk consisted of >1 first‐degree relatives with PC or PC‐associated mutations (i.e. BRCA2, Lynch Syndrome, Familial Atypical Multiple Mole Melanoma Syndrome, STK11, or PALB2)." (PMID 33319059, 2020). "The genetic mutations and syndromes that are linked to PDAC include Peutz-Jeghers syndrome, Lynch syndrome, p16 carriers, BRCA2 mutation, and PALB2 mutation carriers." (PMID 27069714, 2016). "In addition to RAD51C, RAD51D and BRIP1 genes, it would be appropriate for an OC panel to also include PALB2 and Lynch Syndrome genes going forward." (PMID 34503154, 2021).
Lynch syndrome (continued). "Of these, five mutations (9.26%, 5/54) were in homologous recombination repair (HRR) pathway genes, including PALB2 (1.85%, 1/54), BLM (1.85%, 1/54), NBN (1.85%, 1/54), RAD51C (1.85%, 1/54), and RAD51D (1.85%, 1/54), and one mutation was in MSH3 (1.85%, 1/54) related to Lynch syndrome." (PMID 33194720, 2020). "Gene-related cancer predisposition syndromes accounted for 16.7% (4/24) of ACMG SFs: MSH6 Lynch syndrome—1, BRCA1 hereditary breast and ovarian cancer (HBOC)—1, and PALB2 hereditary breast cancer (HBC)—2." (PMID 36635046, 2023). "Thirty-nine patients (2%) were identified as carriers of a PV in an autosomal dominant clinically actionable hereditary breast and ovarian cancer (HBOC)-related or Lynch syndrome gene, most frequently, BRCA2 (6/39; 15.4%), PALB2 (8/39; 20.5%), CHEK2 (10/39; 25.6%), and PMS2 (5/39; 12.8%)." (PMID 37861889, 2024). "PVs in BRCA1, but not BRCA2, PALB2, ATM, CHEK2, or Lynch syndrome genes, were associated with elevated RS on multivariable analysis (P < .001)." (PMID 33426465, 2021).
breast and ovarian cancer (26 papers, 2014 to 2026). "The pathogenic mutations in genes such as MUTYH, FANCD2, NBN, PALB2, and BRCA1 are associated with hereditary breast and ovarian cancer syndrome, an autosomal dominant disorder typically manifesting around age 30 and above." (PMID 41229399, 2025). "In conclusion, we detected a significantly high prevalence of PALB2, BARD1, and BLM mutations, with a low frequency of mutant CHEK2 in the current Japanese cohort of 568 patients with BRCA1/2 WT HBOC syndrome." (PMID 32566746, 2020). "Specific germline mutations in the hereditary breast-ovarian cancer susceptibility (HBC/HBOC) genes, BRCA1, BRCA2 and PALB2, have been shown to recur in French Canadians of Quebec, Canada, and this has been attributed to common ancestors." (PMID 25925845, 2015).
medulloblastoma (23 papers, 2013 to 2026). A malignant, invasive embryonal neoplasm arising from the cerebellum. "Patients with biallelic PALB2 variants belong to the FA-N complementation group and have a predisposition to embryonal tumors of childhood such as medulloblastoma, neuroblastoma, and Wilms tumor, similar to FA-D1 patients." (PMID 40854122, 2025). "So, the mutations in PALB2 normally not only resulted in typical FA phenotypes, but also increased the occurrence of pediatric malignancies, Wilm’s tumors, and medulloblastomas." (PMID 32300589, 2020). "Medulloblastoma (MB) has been described only in few cases of FA with biallelic inactivation in the tumor suppressor gene BRCA2/FANCD1 or its associated gene PALB2/FANCN." (PMID 26064523, 2015). "An example of a study supporting such causality showed that heterozygous pathogenic germline variants in PALB2 and BRCA2 in children with medulloblastoma had somatic mutational signatures typical of PALB2/BRCA2-related homologous recombination repair deficiency in the corresponding tumors." (PMID 34061292, 2021). "In addition to these functions, PALB2 was identified as an associated gene for Fanconi amenia (subtype N, FANCN) and pediatric malignancies such as Wilms’ tumor or medulloblastoma." (PMID 35008774, 2021). "However in two pediatric medulloblastoma patients with mutations in DNA repair genes (PALB2 and BRCA2) chemotherapy inducted grade 4 side effects were reported." (PMID 28376765, 2017). "Brain tumors (mostly medulloblastoma), Wilms tumor, and neuroblastoma are almost exclusively seen in patients with FANCD1/BRCA2 and FANCN/PALB2 variants." (PMID 40970532, 2025). "Six different PALB2 siRNAs (along with five controls) were individually transfected into DAOY medulloblastoma cells, which have a cerebellar origin, to deplete the protein." (PMID 35404932, 2022). "To confirm the genetic interactions between BRCA1 and PALB2 in redox regulation and cell fitness in human cells, we took advantage of our recently generated PALB2 knockout DAOY medulloblastoma cells and the same cells reconstituted with a human PALB2 cDNA." (PMID 33893322, 2021). "Biallelic inactivation mutations in PALB2/FANCN cause Fanconi anemia subtype N, characterized by a severe predisposition to pediatric malignancies such as Wilms tumor, medulloblastoma, AML and neuroblastoma." (PMID 23935836, 2013). "Additionally, biallelic mutations in FANCD1/BRCA2 and FANCN/PALB2 are associated with neuroblastoma, medulloblastoma, and Wilms Tumor." (PMID 40739565, 2025). "Importantly, our analyses of Palb2 CKO mouse brains and PALB2 KO human (DAOY) medulloblastoma cells led to the discovery of a novel role for PALB2 in regulating mitochondrial biogenesis and function." (PMID 35404932, 2022).
medulloblastoma (continued). "To further assess the role of PALB2 in mitochondrial biogenesis/function and its functional relationship with ATG7 in human cells, we used CRISPR/Cas9 to knock out PALB2 and ATG7 in the DAOY medulloblastoma cells." (PMID 35404932, 2022). "Similarly, ATM, NBN, PALB2, PMS2, PTCH1, and SUFU are tumor suppressor and germline risk genes for medulloblastoma, but CH variants in these genes have not been found in prior studies." (PMID 32508881, 2020).
triple-negative breast carcinoma (21 papers, 2012 to 2026). An invasive breast carcinoma which is negative for expression of estrogen receptor (ER), progesterone receptor (PR), and human epidermal growth factor receptor 2 (HER2). "For BRCA1 and PALB2, rare missense variants were associated with an increased risk of overall and triple-negative breast cancer, respectively." (PMID 37790698, 2023). "Increased risk of triple-negative breast cancer was observed for carriers of rare missense variants in PALB2 with an adjusted OR of 5.79 (1.32-25.29 95% CI, p-value = 0.020)." (PMID 37790698, 2023). "In the included patients, 48 had triple-negative breast cancer, the PALB2 mutation prevalence was 4.2 % (2/48)." (PMID 26489409, 2015). "Additionally, single P/LP germline variants in the PTEN and RAD51C genes, as well as a somatic variant in PALB2, were associated with triple-negative breast cancer." (PMID 40710012, 2025). "In addition, rare missense variants in PALB2 were associated with a moderate risk of triple-negative breast cancer." (PMID 37790698, 2023). "PALB2 mutation may be associated with triple-negative breast cancer, the same as immunohistochemical features of BRCA1/2 mutation-associated breast tumors." (PMID 26489409, 2015). "In the triple-negative breast cancer subgroup, the BRCA1/2 double mutation frequency was 0.06% (1/1773), and the BRCA1/2 and PALB2 triple mutation frequency was 0.06% (1/1773)." (PMID 38439896, 2024). "The frequency of pathogenic variants in women with triple negative breast cancer was 23.2%, with 91% of the observed pathogenic variants detected in BRCA1, BRCA2, and PALB2." (PMID 36544278, 2023). "We have recently reported that among 163 BRCA-negative triple-negative breast cancer patients in Cyprus, 4.3% are positive for PVs in PALB2, whereas PALB2 PVs consisted 87.5% of the PVs detected using a panel of 94 cancer susceptibility genes." (PMID 37790698, 2023). "Pathogenic germline mutations in BRCA1, BRCA2, PALB2, RAD51C, and RAD51D, all of which are involved in the HR pathway, are known to confer high or moderate penetrance susceptibility to ovarian and/or triple-negative breast cancer." (PMID 34635660, 2021). "Double heterozygous PALB2 c.758insT and BRCA1 c.927delA mutations have also been identified in a German patient with triple-negative breast cancer." (PMID 34439348, 2021). "Therefore, PALB2 mutation might be associated with triple-negative breast cancer." (PMID 26489409, 2015). "In the present study, we scanned the whole coding regions of BRCA1, BRCA2, PALB2 and BRD7 in order to investigate the relative contributions of germ-line mutations in these genes to triple-negative breast cancer in a hospital-based series of German patients." (PMID 23110154, 2012). "We investigated a hospital-based series of 40 consecutive patients with triple-negative breast cancer for mutations in the whole coding sequences of BRCA1 and BRCA2 as well as in the two genes PALB2 and BRD7, which encode interaction partners of the BRCA1 protein." (PMID 23110154, 2012). "TNBCs (triple negative breast cancers, ER-, PR-, and HER2-) were more commonly found in carriers with BRCA1, BRCA2 or PALB2 PVs." (PMID 35135604, 2022).